ANGPTL8 (angiopoietin like 8)
Diseases named in the same sentence as ANGPTL8 in open-access papers (continued):
Sharing a sentence is not in itself a finding about the gene and the disease.
Obesity (continued). "Results of ROC analysis to evaluate the predictive performance of ANGPTL8 on obesity showed that ANGPTL8 has reasonable predictive power, with an area under curve (AUC) of 0.703 (95% CI 0.648 - 0.759) indicating acceptable accuracy in predicting obesity." (PMID 38189043, 2023). "Our results showed that the protective effect of estrogen on body obesity is related to ANGPTL8." (PMID 36034432, 2022). "However, multiple studies have revealed that the levels of ANGPTL8 are higher in patients with diabetic nephropathy and obesity as well as positively correlated with atherogenic markers and carotid intima-media thickness." (PMID 36143124, 2022). "Meanwhile, we detected the expression levels of ANGPTL8 in mice with HFD-induced obesity." (PMID 36034432, 2022). "This may explain the sex-specific differences demonstrated by us in relation to the effect of obesity on ANGPTL8 levels." (PMID 34959891, 2021). "Six months after bariatric surgery, an increase in plasma ANGPTL8 was observed in patients with obesity submitted to sleeve gastrectomy (pre-surgery 9.34 ± 0.94 vs. post-surgery 10.85 ± 1.13 ng/mL, p < 0.05) and RYGB (pre-surgery 20.76 ± 3.53 vs. post-surgery 47.53 ± 5.47 ng/mL, p < 0.001)." (PMID 34884755, 2021). "It is reported that circulating ANGPTL8 concentrations are different in people with obesity depending on the origins of obesity which may be linked to body composition, basal metabolic rate, or metabolic outcomes." (PMID 30021605, 2018). "To date, the metabolic significance of ANGPTL8 in human obesity and obese patients with PWS is unknown." (PMID 28600576, 2017). "However, the accumulation of ectopic fat is a long-term process, so the effect of ANGPTL8 on long-term diet-induced obesity, especially on lipid deposition in various organs, remains unclear." (PMID 36034432, 2022). "Moreover, circulating and hepatic ANGPTL8 expression in human and experimental obesity-associated NAFLD were increased in relation to the degree of liver steatosis, and both sleeve gastrectomy and RYGB downregulated the ANGPTL8 transcripts in the liver of preclinical models." (PMID 34884755, 2021). "This indicates that ANGPTL8 may be involved in the mechanism of obesity and MetS." (PMID 30524367, 2018). "Plasma ANGPTL8 levels are also increased in individuals with T1DM, T2DM and obesity, and positively correlate with hepatic steatosis in MASLD patients." (PMID 40443802, 2025). "Future studies measuring the levels of sex hormones and body fat compositions along with ANGPTL8 levels in adolescents are required to validate the observed relationships that ANGPTL8, chemerin, leptin, and CRP have with obesity." (PMID 38189043, 2023). "Accumulating evidence reveals that obesity accelerates the secretion of hepatokines from hepatocytes such as hepassocin (HPS), angiopoietin-like protein 8 (ANGPTL8), Fetuin-A and B and fibroblast growth factor 19 and 21 (FGF19/21)." (PMID 37361533, 2023). "Therefore, it is unclear whether ANGPTL8 induces obesity by affecting adipocyte number." (PMID 36034432, 2022). "In the present study, we evaluated plasma ANGPTL8 concentrations 6 months after sleeve gastrectomy and RYGB in patients with obesity and biopsy-proven NAFLD." (PMID 34884755, 2021). "In health, obesity, T2DM and other populations, the correlation between ANGPTL8 and a variety of lipid metabolism indicators has been fully proved." (PMID 34582711, 2021). "Although circulating ANGPTL8 levels have been reported to be related to IR, T2DM, obesity, PCOS, nonalcoholic fatty liver disease (NAFLD), and MetS, ANGPTL8 is mainly secreted and expressed by hepatocytes." (PMID 31346314, 2019). "Serum ANGPTL8 levels were significantly higher (p <0.001) in NAFLD patients (1301.0 ± 617.0 pg/mL) compared to controls (900.0 ± 574.0 pg/mL), even after stratification by obesity or diabetic status." (PMID 40276549, 2025).
Obesity (continued). "The optimal threshold of ANGPTL8 level for distinguishing individuals with obesity from those with no obesity (i.e., both the normal-weight and overweight groups from the category of non-obese individuals) was found to be 122.8 pmol/l." (PMID 38189043, 2023). "When we stratified the analysis by sex, we still observed an elevated level of ANGPTL8 in female and male individuals with obesity compared to normal-weight individuals." (PMID 38189043, 2023). "We found an interesting phenomenon in which the effect of ANGPTL8 on diet-induced obesity was not obvious in female mice." (PMID 36034432, 2022). "We sought to explore whether ANGPTL8 is involved in NAFLD amelioration after bariatric surgery in experimental models and patients with severe obesity." (PMID 34884755, 2021). "We assessed the gender-specific relationships of serum ANGPTL3 and ANGPTL8 with atherogenic lipid biomarkers and obesity in non-diabetic adults." (PMID 34959891, 2021). "In our study, we aimed to assess the gender-specific relationships of serum ANGPTL3 and ANGPTL8 with biomarkers of atherogenic lipid profile and obesity in non-diabetic adults." (PMID 34959891, 2021). "Biopsy-proven NAFLD in patients with obesity was related to increased circulating levels of ANGPTL8 (normal liver 11.94 ± 1.60 vs. NAFLD 20.00 ± 1.96 ng/mL, p = 0.003) in both stages of NAFLD and NASH." (PMID 34884755, 2021). "The differing influence of obesity in women and men on ANGPTL3 and ANGPTL8 concentrations could be explained by differences in body fat distribution as suggested in earlier studies." (PMID 34959891, 2021). "We selected circulating ANGPTL3 and ANGPTL8 to assess gender-specific relationships with obesity and biomarkers of atherogenic lipid profile in non-diabetic adults aged between 25 and 74 years." (PMID 34959891, 2021). "This suggests that ANGPTL5 could be a specific and a more sensitive marker for childhood as well as adult obesity than ANGPTL3 and ANGPTL8." (PMID 32286392, 2020). "Studies have shown that serum angiopoietin-like protein 8 (ANGPTL8) levels are increased in patients with many chronic metabolic diseases (such as type 2 diabetes, obesity, and hepatic steatosis), while the role of ANGPTL8 in ectopic lipid accumulation has not been reported." (PMID 36034432, 2022).
type 2 diabetes (42 papers, 2015 to 2026). "At the same time, in high-risk cohorts with morbid obesity or type 2 diabetes, circulating Angptl8 levels correlate significantly with atherogenic lipid profiles." (PMID 31380419, 2019). "Further studies are needed to validate the causative relationship between ANGPTL8 and subclinical atherosclerosis in type 2 diabetes." (PMID 30007407, 2018). "First, our study is limited by the cross-sectional design and fails to address the causal relationship between albuminuria and ANGPTL8 in type 2 diabetes." (PMID 30072957, 2018). "When we tested the mediator role of TG in the relationship between ANGPTL8 and ACR in type 2 diabetic patients with A2, in the first linear regression equation, ANGPTL8 was positively associated with TG (P < 0.05)." (PMID 30072957, 2018). "Here, we aimed to determine the association of ANGPTL8 p.Q121X with two measures of glucose homeostasis – fasting glucose level and type 2 diabetes status in up to 95,558 individuals (14,824 type 2 diabetics and 80,734 controls)." (PMID 26822414, 2016). "We sought to better understand the importance of ANGPTL8 in human glucose homeostasis by examining the association of a null mutation in ANGPTL8 with fasting glucose levels and risk for type 2 diabetes." (PMID 26822414, 2016). "It is possible that there is a recessive effect on fasting glucose levels or type 2 diabetes status that would be unmasked only in individuals homozygous for the ANGPTL8 mutation." (PMID 26822414, 2016). "Given that the primary analysis suggested that ANGPTL4 and ANGPTL8 PTVs may reduce triglyceride levels, we tested these PTVs’ impact on type 2 diabetes (T2D), coronary artery disease (CAD) risk in 218,792 individuals from the FinnGen Study." (PMID 33909604, 2021). "Binary logistic regression analysis was used to estimate the association of ANGPTL8 with the odds of subclinical atherosclerosis in type 2 diabetes, it revealed that elevated levels of ANGPTL8 were significantly associated with an increased risk of subclinical atherosclerosis in type 2 diabetes." (PMID 30007407, 2018). "Fourth, ANGPTL8 might serve as a novel risk biomarker for subclinical atherosclerosis in type 2 diabetes." (PMID 30007407, 2018). "Second, increased serum levels of ANGPTL8 were positively associated with c-IMT in type 2 diabetes." (PMID 30007407, 2018). "In the type 2 diabetes study, the ANGPTL8 level was found to be related to urinary albumin excretion, and there was a positive correlation between serum ANGPTL8 and urinary albumin/creatinine levels (r = 0.427, P < 0.001)." (PMID 33853533, 2021). "In patients with type 2 diabetes, serum ANGPTL8 was positively correlated with TGs and negatively correlated with CHOL and HDL." (PMID 33853533, 2021). "For example, concomitant presence of CETP B1, NOS3 T and ANGPTL8 T alleles augments the risk of both CHD and type 2 diabetes." (PMID 32000781, 2020). "Recent studies have revealed that ANGPTL8 plays a significant role in several metabolic diseases, in particular, type 2 diabetes mellitus (T2DM), obesity, non-alcoholic fatty liver disease (NAFLD), and polycystic ovary syndrome (PCOS)." (PMID 30900216, 2019). "Our findings suggested of potential role of ANGPTL8 in the pathogenesis of albuminuria in type 2 diabetes." (PMID 30072957, 2018). "Logistic regression analysis revealed that ANGPTL8 had higher odds of having subclinical atherosclerosis [odds ratio (OR) 2.90, 95% confidence interval (CI) 1.48–5.70, P = 0.002] in type 2 diabetes." (PMID 30007407, 2018). "The present study demonstrated that serum ANGPTL8 levels were significantly increased in type 2 diabetic patients with A1, A2, and A3 as compared with control subjects." (PMID 30072957, 2018). "Some studies reported unchanged ANGPTL8 in type 2 diabetes, whereas others reported decreased or increased ANGPTL8 levels." (PMID 30072957, 2018).
type 2 diabetes (continued). "To date, no study has ever evaluated the association between circulating levels of ANGPTL8 and c-IMT or considered the possibility of identifying ANGPTL8 as a risk biomarker for subclinical atherosclerosis in type 2 diabetes." (PMID 30007407, 2018). "Logistic regression analysis indicated that ANGPTL8 had higher odds of having A2 (OR = 2.52, 95% CI 1.16–5.48, P = 0.019) and A3 (OR = 4.89, 95% CI 2.10–11.39, P < 0.001) in type 2 diabetes." (PMID 30072957, 2018). "There have been a number of studies showing increased circulating levels of ANGPTL8 in type 2 diabetic patients and also studies on unaltered or decreased circulating levels of ANGPTL8." (PMID 30007407, 2018). "Our data provide the first evidence for a strong link between ANGPTL8 and subclinical atherosclerosis, suggesting ANGPTL8 to be a new biomarker for subclinical atherosclerosis in type 2 diabetes." (PMID 30007407, 2018). "Confusingly, ANGPTL8 levels are either increased or decreased in the serum of type 2 diabetes patients." (PMID 25917759, 2015). "Furthermore, our data indicated that serum levels of ANGPTL8 had higher OR for albuminuria in type 2 diabetic patients, suggesting ANGPTL8 to be a new biomarker for albuminuria in type 2 diabetes." (PMID 30072957, 2018). "However, given the cross-sectional design of the study, it is hard to conclude that TG mediates the impact of ANGPTL8 on albuminuria in type 2 diabetes." (PMID 30072957, 2018). "Our data provide the evidence for a strong link between ANGPTL8 and albuminuria, indicating that ANGPTL8 may be a new biomarker for diabetic kidney disease in type 2 diabetes." (PMID 30072957, 2018). "Hence, we aimed to explore the correlations between serum levels of ANGPTL8 and subclinical atherosclerosis in type 2 diabetes." (PMID 30007407, 2018). "First, this study is an epidemiological cross-sectional research and somehow fails to address the causal role of ANGPTL8 in the pathogenesis of subclinical atherosclerosis in type 2 diabetes, which is needed to be elucidated by further investigation." (PMID 30007407, 2018). "However, contradictory results of ANGPTL8 in glucose metabolism have been reported in patients with type 2 diabetes." (PMID 26739706, 2016). "We find that carrying a null mutation in human ANGPTL8 is neither associated with fasting glucose nor risk for type 2 diabetes in analyses involving up to 95,558 individuals." (PMID 26822414, 2016). "If such counter-regulatory loops protect Angptl8 expression levels, this could challenge the potential therapeutic utility of interventions to augment Angptl8 expression in type 2 diabetes." (PMID 25917759, 2015). "Hence, we aimed to explore the relationship between ANGPTL8 and albuminuria in type 2 diabetes." (PMID 30072957, 2018). "Therefore, we were motivated to hypothesize that increased circulating levels of ANGPTL8 might be positively associated with common carotid artery Intima-Media Thickness (c-IMT) and serve as a novel biomarker for atherosclerosis in type 2 diabetes." (PMID 30007407, 2018). "In conclusion, we found that serum ANGPTL8 levels were significantly increased in type 2 diabetic patients with albuminuria, moreover, our data provided the evidence that ANGPTL8 was positively correlated with urine ACR in this population and TG might partially mediated this positive correlation." (PMID 30072957, 2018). "Consequently, it is speculated that antidiabetic treatments might, at least in part, lead to this obscure or nonsignificant relationship between blood glucose, insulin resistance and ANGPTL8 in type 2 diabetes." (PMID 30007407, 2018). "In patients with type 2 diabetes, the elevated serum triglyceride levels negatively correlate with circulating LPL levels, and positively with circulating APOC1, APOC3, ANGPTL3, ANGPTL4 and ANGPTL8 levels." (PMID 37448184, 2023). "Serum levels of ANGPTL8 were significantly higher in DN compared with type 2 diabetes patients without DN." (PMID 37448184, 2023).
type 2 diabetes (continued). "The analysis of the mediator role of TG in the relationship between ANGPTL8 and ACR in type 2 diabetic patients with A3 group showed similar results, such that TG may be considered as partial mediator." (PMID 30072957, 2018). "Multivariate binary logistic regression without adjustment demonstrated that serum ANGPTL8 levels were significantly related to A2 [odds ratio (OR) 2.49 (95% CI 1.17–5.32), P = 0.019] and A3 [4.51 (95% CI 2.01–10.12), P < 0.001] in type 2 diabetes." (PMID 30072957, 2018). "Some studies found that serum ANGPTL8 levels were elevated in patients with type 2 diabetes compared to subjects with nondiabetic subjects." (PMID 26739706, 2016). "While our results do not support the role of ANGPTL8 inhibitors for treatment of type 2 diabetes, there remains evidence that ANGPTL8 inhibition remains a viable anti-triglyceride target." (PMID 26822414, 2016). "Consequently, one possible explanation for the positive correlation between ANGPTL8 and ACR is that ANGPTL8 might be involved in the pathogenesis of albuminuria in type 2 diabetes through increasing TG levels." (PMID 30072957, 2018). "Consequently, these findings above motivated us to speculate that increased circulating levels of ANGPTL8 might be positively related to urine albumin-to- creatinine ratio (ACR) and serve as a novel biomarker for diabetic kidney disease in type 2 diabetes." (PMID 30072957, 2018).
hypertriglyceridemia (28 papers, 2015 to 2025). A laboratory test result indicating elevated triglyceride concentration in the blood. "In another study, circulating ANGPTL8 concentrations were an important factor positively associated with fasting hypertriglyceridemia in diabetic patients, while negatively correlated with levels of HDL-C." (PMID 40607224, 2025). "ANGPTL8 increased the risk of hypertriglyceridemia by almost 33% and remnant cholesterol by 24%, and these effects were highly significant." (PMID 34959891, 2021). "Regression models, adjusted for age, sex, and BMI showed a weak but significant effect of ANGPTL8 to increase the risk of hypertriglyceridemia." (PMID 34959891, 2021). "In females, ANGPTL8 was found to be of very good diagnostic ability in identifying subjects with hypertriglyceridemia (AUC = 0.83), similar to that of remnant-C and sdLDL-C (AUC = 0.87), though the power of discrimination of ANGPTL3 was much lower (AUC = 0.71)." (PMID 34959891, 2021). "The hepatic overexpression of Angptl8 causes hypertriglyceridemia and increased insulin secretion." (PMID 31380419, 2019). "For example, it has been shown that angiopoietin-like protein 8 (ANGPTL8) is involved in hypertriglyceridemia through the inhibition of the lipoprotein lipase enzyme, which is responsible for triglyceride breakdown." (PMID 41373434, 2025). "It must be noted that the prediction power of ANGPTL8, as an early indicator of TG increase, was comparable to that for moderate hypertriglyceridemia (OR per unit increase = 1.495; p < 0.001)." (PMID 35736472, 2022). "We focused on the observation that ANGPTL3 is required by ANGPTL8 to inhibit LPL and the co-expression of ANGPTL3 and ANGPTL8 induces more pronounced hypertriglyceridemia than the overexpression of ANGPTL3 alone." (PMID 34293055, 2021). "Among predictors of hypertriglyceridemia, ANGPTL8 was the best positive predictor in women, whereas the effect of ANGPTL3, though significant, was very low irrespective of gender." (PMID 34959891, 2021). "Multiple regression analysis indicated that low LPL, high ApoC2, high ApoC3, high ApoE, and high ANGPTL8 levels were the determinants of fasting hypertriglyceridemia." (PMID 34293055, 2021). "The models in the multivariable analysis revealed that ANGPTL8 and remnant cholesterol were the best positive predictors of hypertriglyceridemia in women." (PMID 34959891, 2021). "Many studies have confirmed that overexpression of ANGPTL8 can lead to impaired clearance of circulating TG, leading to hypertriglyceridaemia, while knockdown or inhibition of ANGPTL8 can significantly reduce the level of circulating TG." (PMID 34582711, 2021). "In women alone, ANGPTL8 showed very good discrimination power to identify subjects with hypertriglyceridemia (AUC = 0.83)." (PMID 34959891, 2021). "Of note, overexpression of Angptl3 alone does not alter the levels of circulating TG, whereas co-expressing it with Angptl8 results in hypertriglyceridemia in mice." (PMID 27845381, 2016). "Further studies are needed to explore the biological mechanisms involving ANGPTL8 in the pathogenesis of hypertriglyceridemia." (PMID 26739706, 2016). "Although plasma TG levels did not change in mice overexpressing ANGPTL3 alone, co-overexpression of ANGPTL3 and ANGPTL8 resulted in hypertriglyceridemia." (PMID 26739706, 2016). "Taken together, these evidences reveal an intuitively mechanism of Angptl3/ Angptl8-mediated hypertriglyceridemia induced by LXRs." (PMID 27845381, 2016). "Expression of ANGPTL8 was reduced by fasting in humans, while overexpression of ANGPTL8 resulted in hypertriglyceridemia." (PMID 26004022, 2015). "Various types of stress, such as oxidative stress or dietary excess that contributes to hyperglycemia and hypertriglyceridemia, which are well-documented risk factors for the pathogenesis of NAFLD, also lead to enhanced hepatic ANGPTL8 production and secretion." (PMID 36983346, 2023).